SMAD1 (SMAD family member 1)
Diseases named in the same sentence as SMAD1 in open-access papers (continued):
Sharing a sentence is not in itself a finding about the gene and the disease.
cardiac arrest (1 paper, 2025). Cessation of breathing and/or cardiac function. "Pro-EMT markers phospho-Smad1/5, Sox9, and Twist1 were downregulated in the AVC endocardium after cardiac arrest." (PMID 39932433, 2025).
chondrodysplasia (1 paper, 2022). "Smad1/5 knock‐out in mice has demonstrated severe chondrodysplasia, and the loss of BMP‐Smad1/5 signaling causes the reduction of chondrocyte proliferation and elevated apoptosis." (PMID 36536500, 2022).
chronic myelogenous leukemia (1 paper, 2014). "Of note, studies from the Zon laboratory showed BMP2 treatment of K562 and U937 recruited phosphor SMAD1 with lineage specific factors (erythroid factor GATA1 in K562 cells derived from chronic myelogenous leukemia in erythroid blast crisis and CEBPA in U937 myelomonocytic cells)." (PMID 25544748, 2014).
clear cell renal carcinoma (1 paper, 2015). A malignant epithelial neoplasm of the kidney characterized by the presence of lipid-containing clear cells within a vascular network. "For example, it was previously indicated that SOSTDC1 is significantly down-regulated in clear cell renal carcinoma and over-expression of SOSTDC1 inhibits its proliferation through suppressing BMP-7-induced phosphorylation of Smad-1, -5, and -8, as well as Wnt-3a signaling." (PMID 26378658, 2015).
disc degeneration (1 paper, 2019). "Our results demonstrated that miR‐26a‐5p induction, Smad1 down‐regulation and Vegfa increase are associated with disc degeneration." (PMID 31338931, 2019). "As disc degeneration involves osteogenesis of disc tissues, we perturbed miR‐26a‐5p or Smad1 in disc cells to study their alkaline phosphatase (ALP) activity, a marker of osteogenesis." (PMID 31338931, 2019). "Thus, our results suggested that Vegfa induction in disc degeneration requires negative regulation of Smad1 by miR‐26a‐5p." (PMID 31338931, 2019). "In summary, we established a method that consistently profiles circulating miRNAs and identified multiple miRNAs as promising biomarkers for disc degeneration, among which miR‐26a‐5p enhances VEGF expression during disc degeneration through targeting Smad1 signalling." (PMID 31338931, 2019). "Collectively, our results confirmed a role of miR‐26a‐5p in disc degeneration by promoting VEGF‐A expression through repression of Smad1, which may be key event in the invasion of blood vessels in degenerated disc tissues." (PMID 31338931, 2019). "Moreover, we found that miR‐26a‐5p targets Smad1 expression, and Smad1 negatively regulates Vegfa expression in disc cells, and thus, miR‐26a‐5p promotes disc degeneration." (PMID 31338931, 2019).
Eisenmenger syndrome (1 paper, 2022). "Of them, three had at least one P or LP variant: one patient with PAH after the closure of a ventricular septal defect (SOX17), one individual with PAH associated with incidental defects (ABCC8 and SMAD1), and the remaining one with a complex Eisenmenger syndrome (BMPR2)." (PMID 36142358, 2022).
emphysema (1 paper, 2012). "The changing expression of SMAD6 and SMAD1, their localization predominantly to vascular endothelial cells, and the roles of ACVRL1 and ENG in angiogenesis support the hypothesis of aberrant tissue remodeling in the lung vasculature during emphysema pathogenesis." (PMID 22937864, 2012).
endometrial disorder (1 paper, 2023). A non-neoplastic or neoplastic disorder that affects the endometrium. "Smad1/5 cKO mice showed endometrial receptivity defects and perturbed embryo implantation, and Smad2/3 cKO mice showed endometrial disorders, sterility, and uterine cancer." (PMID 37947633, 2023).
endometriosis (1 paper, 2024). The growth of functional endometrial tissue in anatomic sites outside the uterine body. "We consistently observed alterations in the BMP/SMAD1/5/4 signaling pathway in the decidualizing stromal cells from individuals with endometriosis, suggesting that inherent defects in the activation of this pathway were present in the affected individuals." (PMID 38402336, 2024). "In our present study, we found that the decreased decidualization potential of stromal cells from individuals with endometriosis correlated with defective BMP/SMAD1/5 activation." (PMID 38402336, 2024). "We also observed persistent downregulation of the classical BMP/SMAD1/5/4 target genes, ID2 and ID3, suggesting that impaired BMP signaling was resulting in decreased transcriptional activation by SMAD1/5/4 in stromal cells derived from individuals with endometriosis." (PMID 38402336, 2024). "However, given that SMAD4 enrichment was decreased at the ID1 and ID3 promoter regions, and this corresponds with decreased ID gene expression, it was likely that BMP signaling pathways also impair SMAD1/5/4 binding activities in the stromal cells from individuals with endometriosis." (PMID 38402336, 2024). "Our time course transcriptomic analyses revealed that BMP ligands and SMAD1/5/4 transcriptional targets, ID2 and ID3, were consistently downregulated in stromal cells from individuals with endometriosis during in vitro decidualization." (PMID 38402336, 2024). "Given that BMP/SMAD1/5/4 signaling is essential for implantation and decidualization, our goal was to investigate the mechanisms that underpin defective BMP signaling in individuals with endometriosis during decidualization at the transcriptional level." (PMID 38402336, 2024). "We focused on the roles of BMP/SMAD1/5 signaling given that we observed altered expression of BMP ligands (BMP4, BMP6) as well as decreased expression of canonical SMAD1/SMAD5 targets in the decidualizing stromal cells from individuals with endometriosis." (PMID 38402336, 2024). "In the samples from individuals without endometriosis (n = 5), SMAD1/5, the signal transducers of the BMPs, were activated in a time-dependent manner." (PMID 38402336, 2024). "To functionally examine the role of BMP signaling pathway in mediating decidualization, we perturbed the SMAD1/5 complex using small interfering RNA (siRNA) in endometrial stromal cells from individuals without endometriosis and treated them with EPC to induce in vitro decidualization." (PMID 38402336, 2024). "The canonical SMAD1/5 target genes, ID2 and ID3, were significantly decreased during days 4 and 6 of EPC treatment in the endometrial stromal cells derived from individuals with endometriosis relative to those without." (PMID 38402336, 2024).
enthesopathy (1 paper, 2023). "Similar to Hyp entheses, C–/– entheses develop an expansion of SafO+, ALP+ cells that are immunoreactive for p-SMAD1/5/8, PTCH, and RUNX2 by P14, thus demonstrating that enthesopathy in both Hyp and C–/– mice develops early in the postnatal period." (PMID 37490334, 2023).
esophageal squamous cell carcinoma (1 paper, 2022). Esophageal squamous cell carcinoma (ESCC) is a type of esophageal carcinoma (EC) that can affect any part of the esophagus, but is usually located in the upper or middle third. "In esophageal squamous cell carcinoma, Mir-205-5p affects tumor immune response by targeting SMAD1." (PMID 35712349, 2022).
gastric ulcer (1 paper, 2022). An ulcerated lesion in the mucosal surface of the stomach. "Additionally, OS also improves the host immunity by increasing SMAD1/5/8 expression, while the anti-oxidant Cb has been reported to protect against gastric ulcers and functions as a nutritional supplementation due to high-soluble amino acid and mineral levels in Cb." (PMID 36204231, 2022).
glomerular disease (1 paper, 2016). "So far, no study has addressed the effect of gene ablation of Smad1 in glomerular disease because conventional Smad1 knockout mice are embryonic lethal." (PMID 27492138, 2016).
head and neck squamous cell carcinoma (1 paper, 2020). A squamous cell carcinoma that arises from any of the following anatomic sites: lip and oral cavity, nasal cavity, paranasal sinuses, pharynx, larynx, and salivary glands. "Results from our gene expression profiling study are in broad agreement with previous studies performed on non-small-cell lung cancer (NSCLC) and head and neck squamous cell carcinoma (HNSCC), where greater than 95% of cases have been shown to overexpress BMP2, phosphorylated SMAD1/5, and Id1." (PMID 32708289, 2020).
hemochromatosis (1 paper, 2025). A disorder of iron metabolism characterized by a triad of HEMOSIDEROSIS; LIVER CIRRHOSIS; and DIABETES MELLITUS. "The hepatocyte Smad1/5/8 knockout murine model of hemochromatosis revealed an important role of SMAD8 in hepcidin regulation and demonstrated that testosterone and epidermal growth factor (EGF) require SMAD1/5/8 to regulate hepcidin production." (PMID 40149659, 2025).
Hodgkins lymphoma (1 paper, 2024). A heterogeneous group of malignant lymphoid neoplasms of B-cell origin characterized histologically by the presence of Hodgkin and Reed-Sternberg (HRS) cells in the vast majority of cases. "For example SMAD1 levels are particularly low in DLBCL subtypes, but also in Hodgkin lymphoma." (PMID 39834944, 2024).
ischemic heart disease (1 paper, 2017). "In ischemic heart disease, FSTL1 prevents myocytes apoptosis through inhibiting BMP4-p-Smad1/5/8 signaling and enhancing AMPK pathway." (PMID 28852126, 2017).
kidney cancer (1 paper, 2024). Primary or metastatic malignant neoplasm involving the kidney. "The aim of the study was to verify hypotheses: Are transforming growth factors TGFβ1-3, their receptors TGFβI-III, and intracellular messenger proteins Smad1-7 involved in the pathogenesis of kidney cancer?" (PMID 38085441, 2024).
leiomyoma (1 paper, 2007). A well-circumscribed benign smooth muscle neoplasm characterized by the presence of spindle cells with cigar-shaped nuclei, interlacing fascicles, and a whorled pattern. "They included several genes such as NR2F1, PNN, Smad4, Smad5, STAT5B, JUN, TGIF2, and ATF1 that were over-expressed while RUNX3, STAT1, STAT6, EGR3, GAS7, Smad1, and EDF1 were underexpressed in leiomyomas as compared to keloid/incisional scars." (PMID 17718906, 2007).
Lewis lung carcinoma (1 paper, 2020). "Nuclear Smad1 staining was usually found in CK18+ LLCs in metastatic bone tumours, indicating that BMP signalling of Lewis lung carcinoma cells were activated in bone metastases." (PMID 32750747, 2020). "We stained Lewis lung carcinoma cells with CK18 and Smad1 to further confirm that BMP signalling was activated in Lewis lung carcinoma cells rather than other cell types of metastatic bone tumours." (PMID 32750747, 2020).
medulloblastoma (1 paper, 2025). A malignant, invasive embryonal neoplasm arising from the cerebellum. "Active BMP signaling, detected as nuclear and phosphorylated SMAD1/5, characterized several medulloblastoma subgroups, with enrichment in Group 4, SHH and Group 3 tumors." (PMID 40148468, 2025).
mesangial sclerosis (1 paper, 2018). "Podocyte-specific Bmp4 tgm showed typical mesangial sclerosis accompanied by podocyte loss and increased phosphorylated Smad1 levels in mesangial cells." (PMID 30158674, 2018). "Thus, podocyte loss itself is responsible for mesangial sclerosis, and the increased BMP4 expression observed in podocytes induces Smad1 activation in mesangial cells in a paracrine fashion." (PMID 30158674, 2018).
metastatic cancers (1 paper, 2019). A carcinoma which has spread from the original site of growth to another anatomic site. "SMAD1 was highly expressed in metastatic cancers in bone, but not in primary tumors that developed bone-only metastasis." (PMID 31222004, 2019).
myeloid malignancies (1 paper, 2023). "Furthermore, SMAD1 pathway has been shown to be active in a model of persisting LSCs, suggesting that this factor may be relevant in the development of myeloid malignancies." (PMID 36629404, 2023).
Nephropathy (1 paper, 2016). A nonspecific term referring to disease or damage of the kidneys. "We investigated the role of Smad1 in an experimental nephropathy model using Smad1-CKO mice." (PMID 27492138, 2016).
oral cancer (1 paper, 2023). "Considering that ID3 expression, which is a target gene of both Smad1/5/9 and p38, was increased by CCN6 combined with BMP2, and that production of CCN6 and BMP2 increased in the cells before EMT, it is suggested that CCN6 combined with BMP2 suppresses EMT of oral cancer cells in primary lesions." (PMID 37590989, 2023).
Osteochondroma (1 paper, 2017). A common, benign cartiliginous neoplasm arising from the metaphysis of bone. "We found previously that the onset of osteochondroma formation in conditional Ext1-deficient mice is accompanied by ectopic expression of phosphorylated SMAD1/5/8 proteins in perichondrium that mediate canonical BMP signaling and are pro-chondrogenic." (PMID 28445472, 2017).
Peritoneal Fibrosis (1 paper, 2021). Disorder characterized by a wide range of structural changes in PERITONEUM, resulting from fibrogenic or inflammatory processes. "One possibility is that Gremlin1 can activate the TGFβ pathway and inhibit the expression of BMP7 and Smad1/5/8, thereby inducing peritoneal fibrosis." (PMID 34721005, 2021). "It remains unknown whether BMP7 and Gremlin are expressed in peritoneal tissue, and whether the BMP7/Smad1/5/8 pathway in involved in peritoneal fibrosis." (PMID 34721005, 2021).
proliferative glomerulonephritis (1 paper, 2011). A constellation of renal disorders characterized by an increase number of cells in the glomerulus; these disorders generally present with nephrotic syndrome, and generally progress to end stage renal failure over a matter of weeks to years, depending on the etiology. "Taking these results together, we hypothesized that the Src/Smad1 pathway may be critical in the pathogenesis of proliferative glomerulonephritis." (PMID 21445358, 2011). "Because it is generally accepted that the AngII blockade significantly delays the progression of proliferative glomerulonephritis, our previous findings implied that the inhibition of the Src-Smad1 axis may partially explain the AngII-induced progression of proliferative glomerunonephritis." (PMID 21445358, 2011).
Pulmonary hypoplasia (1 paper, 2016). "SMAD1 plays a key role in organogenesis, including in lung development and maturation, and SMAD1-knockout mice display reduced sacculation, which is an important feature of pulmonary hypoplasia ?" (PMID 26744354, 2016).
pulpitis (1 paper, 2023). Inflammation of the dental pulp. "Moreover, the overexpression of BMP9 might inhibit inflammation in the early stage of pulpitis by the Smad1/5 and ERK/JNK-MAPK pathways." (PMID 36700591, 2023).
renal carcinoma (1 paper, 2021). A carcinoma arising from the epithelium of the renal parenchyma or the renal pelvis. "MiR-196a promotes renal cancer cell migration by directly targeting Bram1 and inhibits Smad1/5/8 phosphorylation and MAPK pathways through BMPR1A and EGFR." (PMID 34803496, 2021).
renal dysplasia (1 paper, 2024). Renal dysplasia is a form of renal malformation in which the kidney(s) are present but their development is abnormal and incomplete. "Previous study shows that phospho-SMAD1 and β-catenin are overexpressed in human fetal dysplastic renal tissue suggesting that dysregulation of these signaling effectors is pathogenic in human renal dysplasia." (PMID 39310276, 2024).
Right ventricular hypertrophy (1 paper, 2022). In this case the right ventricle is more muscular than normal, causing a characteristic boot-shaped (coeur-en-sabot) appearance as seen on anterior- posterior chest x-rays. "Furthermore, the mice with conditional knockout of the Smad1 gene by disrupting Smad1 either in endothelial cells or in smooth muscle cells displayed increased pulmonary pressure, right ventricular hypertrophy, and thickened pulmonary arterioles." (PMID 35281600, 2022).
seminoma (1 paper, 2015). A radiosensitive malignant germ cell tumor found in the testis (especially undescended), and extragonadal sites (anterior mediastinum and pineal gland). "Previously, we were able to show that during in vitro differentiation of TCam-2 cells into a mixed non-seminoma the activity of BMP signaling-related SMAD1 /5 /8 molecules was reduced." (PMID 26226633, 2015). "In CIS, seminomas and ECs, expression of BMP8B, BMPR1A /2, SMAD1 /4 and ID1 /2 was detected, while ID3 expression was restricted to ECs." (PMID 26226633, 2015).
Splenomegaly (1 paper, 2025). Abnormal increased size of the spleen. "Furthermore, rubiadin reversed splenomegaly and elevation of serum iron caused by high-iron diet; notably, rubiadin further increased the hepcidin expression and the phosphorylation of SMAD1/5/9 on the basis of high-iron-fed mice." (PMID 39941155, 2025).
steatosis (1 paper, 2025). Increased lipid within the cytoplasm of cells. "We demonstrate that tilorone attenuated HFD-induced steatosis by restoring bone morphogenetic protein 9 (BMP9)-Smad1/5/8 signaling and upregulating peroxisome proliferator-activated receptor gamma (PPARγ) expression." (PMID 40423936, 2025).
sudden cardiac arrest (1 paper, 2017). Unexpected rapid natural death due to cardiovascular collapse within one hour of initial symptoms. "SMAD1 polymorphism was reported to be associated with sudden cardiac arrest in CAD patients." (PMID 28595632, 2017).
testicular cancer (1 paper, 2012). A primary or metastatic malignant neoplasm that affects the testis. "R-Smads have previously been shown to have a tumor-suppressive role, as gonade-specific deletion of SMAD1/5 induces ovarian or testicular cancer in mice." (PMID 23049692, 2012).
Ureteral obstruction (1 paper, 2016). Obstruction of the flow of urine through the ureter. "Smad1 mediated the BMP7-Alk3 signaling pathway to antagonize epithelial–mesenchymal transition and favor mesenchymal–epithelial transition in unilateral ureteral obstruction, which is a well-established model of severe renal interstitial injury and fibrosis." (PMID 27703192, 2016).